ACSS2 (acyl-CoA synthetase short chain family member 2)
Description:
Catalyzes the synthesis of acetyl-CoA from short-chain fatty acids. Acetate is the preferred substrate. Can also utilize propionate with a much lower affinity. Catalyzes the conversion of lactate into lactoyl-CoA. Does not catalyze the conversion of butyrate or crotonate to their corresponding acyl-CoAs. Nuclear ACSS2 promotes glucose deprivation-induced lysosomal biogenesis and autophagy, tumor cell survival and brain tumorigenesis. Glucose deprivation results in AMPK-mediated phosphorylation of ACSS2 leading to its translocation to the nucleus where it binds to TFEB and locally produces acetyl-CoA for histone acetylation in the promoter regions of TFEB target genes thereby activating their transcription. The regulation of genes associated with autophagy and lysosomal activity through ACSS2 is important for brain tumorigenesis and tumor survival. Acts as a chromatin-bound transcriptional coactivator that up-regulates histone acetylation and expression of neuronal genes (By similarity). Can be recruited to the loci of memory-related neuronal genes to maintain a local acetyl-CoA pool, providing the substrate for histone acetylation and promoting the expression of specific genes, which is essential for maintaining long-term spatial memory (By similarity).
Synonyms: ACS; AceCS; AceCS1; ACAS2; ACSA; dJ1161H23.1
Tractability: Small molecule: a high-quality ligand is known. PROTAC: ubiquitination databases record sites on it; its protein half-life has been measured; a small molecule that binds it is known.
Target class: Enzyme; Ligase
Safety:
Unwanted effects reported when the protein is acted on. In parentheses: how it was acted on, where the effect was seen, and who reports it.
alcoholism (source: ClinPGx)
Gene: Protein-coding gene on chromosome 20 (34,872,146 to 34,927,962, forward strand). Ensembl gene ENSG00000131069.
Subcellular location: Cytoplasm, cytosol; Cytoplasm; Nucleus
Subcellular location (Human Protein Atlas): Nucleoplasm; Cytosol; Plasma membrane; Vesicles
Pathways (Reactome):
Metabolism: Ethanol oxidation
Organelle biogenesis and maintenance: Transcriptional activation of mitochondrial biogenesis
Gene Ontology:
Molecular function: acetate-CoA ligase activity; protein binding; AMP binding; chromatin binding; propionate-CoA ligase activity; transcription coactivator activity
Biological process: lipid biosynthetic process; acetyl-CoA biosynthetic process; ethanol catabolic process; long-term memory; acetate biosynthetic process; positive regulation of DNA-templated transcription; propionate biosynthetic process
Cellular component: cytosol; nucleoplasm; nucleus; cytoplasm; mitochondrial matrix
Genetic constraint (gnomAD): Loss-of-function variants: 49 observed, 79.15 expected, observed/expected ratio (o/e) 0.62, 90% interval 0.49 to 0.79. The upper end of that interval is the gene's LOEUF score, 0.79, which puts it in group 3 of 6, group 1 being the genes least tolerant of losing a copy. Missense variants: 714 observed, 846.81 expected, observed/expected ratio (o/e) 0.84, 90% interval 0.79 to 0.9. Synonymous variants: 281 observed, 307.05 expected, observed/expected ratio (o/e) 0.92, 90% interval 0.83 to 1.01.
Homologues: Orthologues: chimpanzee ACSS2 (99% identical), macaque ACSS2 (99% identical), rabbit ACSS2 (95% identical), dog ACSS2 (94% identical), rat Acss2 (94% identical), mouse Acss2 (94% identical), guinea pig ACSS2 (92% identical), pig ACSS2 (91% identical), tropical clawed frog acss2 (75% identical), Drosophila melanogaster AcCoAS (60% identical), Caenorhabditis elegans acs-19 (51% identical), zebrafish acss2 (49% identical). Paralogues in human: ACSS1 (45% identical), ACSS3 (32% identical), ACSM5 (24% identical), ACSM3 (23% identical), AACS (23% identical), ACSM1 (23% identical), ACSM2A (23% identical), ACSM4 (22% identical), ACSM2B (22% identical), ACSF3 (17% identical), ACSF2 (16% identical), ACSM6 (15% identical), and 1 more.
Diseases named in the same sentence as ACSS2 in open-access papers:
ACSS2 is named in the same sentence as 99 diseases in open-access papers, as found by Europe PMC text mining. Sharing a sentence is not in itself a finding about the gene and the disease. The quoted sentences say what the papers report.
breast carcinoma (24 papers, 2017 to 2026). "In breast cancer cells with long-term estrogen deprivation, the treatment of ACSS2 inhibitor leads to significant loss of viability and proliferation." (PMID 39086974, 2022). "Moreover, immunohistochemical analysis of tumor tissues from 154 patients with breast cancer with a high expression of ACSS2 is associated with a shorter overall survival." (PMID 35740562, 2022). "Results showed that four acyl-CoA synthetases—GCDH, ACSS2, ACOX1, and ACOX3—were significantly down-regulated in breast cancer cells, with ACSS2 showing the most pronounced reduction." (PMID 41544165, 2026). "Results demonstrated that overexpression of ACSS2 notably decreased EZH2 levels in breast cancer cells, whereas ACSS2 knockdown resulted in a marked increase in EZH2 levels." (PMID 41544165, 2026). "Human breast cancers overexpress Acetyl-CoA synthetase-2 (ACSS2), and are thus critically dependent on acetate for lipid synthesis." (PMID 39886047, 2025). "Hypoxia has been shown to upregulate the lipid metabolism-related gene ACSS2 in prostate and breast cancers." (PMID 38263056, 2024). "Tamoxifen can induce increased ACSS2 expression in breast cancer cells, leading to treatment resistance, and the combination of ACSS2 inhibitors can reverse this resistance, thereby increasing tamoxifen-induced cell death." (PMID 38887280, 2024). "This study identifies selective brain-penetrant ACSS2 inhibitors with efficacy towards breast cancer brain metastasis." (PMID 38818373, 2024). "Several small molecules targeting ACSS2 have been identified and tested in liver and breast cancer models." (PMID 38818373, 2024). "Our study, for the first time, shows that treating mice that contain breast cancer brain metastatic macrometastasis with an ACSS2 inhibitor is effective in shrinking tumors in the brain parenchyma and also can extend survival of these mice." (PMID 38818373, 2024). "Acetyl-CoA synthetase 2 (ACSS2) is amplified in breast cancers and targeting ACSS2 impaired tumor growth in TNBC." (PMID 37046596, 2023). "Recent studies have reported that 4-hydroxytamoxifen (4-OHT) induces ACSS1 and ACSS2 mRNA and protein expression in estrogen receptor-α-positive (ER+) breast cancer cells and derived 4-OHT-resistant cells to increase their survival." (PMID 35798917, 2022). "Another finding remains that the high expression of ACSS2 had a protective effect on breast cancer patients." (PMID 35740562, 2022). "The developed ACSS2 inhibitor was able to reduce cell viability in the breast cancer cell line MDA-MB-468 as well as in subcutaneous xenografts in mice." (PMID 35798917, 2022). "In human breast tumors, the ACSS2 copy number is increased, promoting breast cancer cell growth under hypoxic and low-fat conditions through acetate uptake." (PMID 35798917, 2022). "Data have shown an overexpression of ACSS-2 in different types of cancer, such as breast carcinomas, hepatocellular carcinomas." (PMID 36578540, 2022). "It has been proven that ACSS2 is highly expressed in glioblastoma, breast cancer, liver cancer, prostate cancer, bladder cancer, renal cancer, and other tumors, and is closely related to tumor stage and the overall survival rate of patients." (PMID 35740562, 2022). "Although inhibition of ACSS2 has been shown to result in decreased growth of breast cancer, it was shown to significantly decrease the proliferation of the RCC cells only in rapamycin combinations in our in vitro study." (PMID 36142502, 2022). "A clinical phenomenon has also been observed that breast cancer patients with a high expression of ACSS2 have a shorter survival time." (PMID 35740562, 2022). "It has been found that rapamycin binds to ACSS2 to promote the expression of ACSS2 to inhibit the progression of cadmium-mediated breast cancer." (PMID 35740562, 2022).
breast carcinoma (continued). "There are also some findings to the contrary: for example, rapamycin can effectively bind to ACSS2 to mitigate the cadmium-decreased levels of ACSS2 and thus inhibit the progression of breast cancer." (PMID 35740562, 2022). "VY-3–135 is a potent and selective ACSS2 inhibitor that inhibits ACSS2 activity both in vitro and in vivo and inhibits in vivo tumor growth in breast cancers with high ACSS2 expression." (PMID 35798917, 2022). "A recent study described a transition-state mimetic that binds Acss2 in the amino globular region and impedes Acss2 function in breast cancer." (PMID 34343565, 2021). "We find that ACSS2 staining is prominent in tumors of the MMTV-PyMT model of breast cancer and that the intensity of nuclear staining increases in the hypoxic regions of the tumor." (PMID 28099844, 2017). "Based on these findings, ACSS2 may act as a tumor suppressor in breast cancer and is proposed as a candidate enzyme responsible for mediating the inhibitory effect of crotonate." (PMID 41544165, 2026). "Having identified compounds that bind to and inhibit ACSS2 in vitro, we sought to determine whether they had biological effects on brain-tropic breast cancer cells." (PMID 38818373, 2024). "ACSS2 also plays a crucial role in cell growth in various cancers, such as breast cancer." (PMID 39770478, 2024). "Further exploration of ACSS2 as a potential target may lead to innovative strategies for improving the efficacy of breast cancer treatment." (PMID 39351241, 2024). "ACSS2 is highly expressed in several cancers, including breast cancer, and ACSS2 inhibitors have been proposed to treat cancers in a patent by a drug discovery company, Metabomed Ltd., based in Yavne, Israel, with promising potential in the application to clinical practice." (PMID 39519507, 2024). "Whether in a breast cancer cell line or a prostate cancer cell line, hypoxia and a low serum can significantly increase the expression of ACSS2, which in turn promotes cell survival under metabolic stress." (PMID 35740562, 2022). "Under stress, downregulation of ACSS2 expression was found to reduce the growth of xenograft tumors, suggesting that ACSS2 plays an important role in tumor cell survival and growth in the harsh breast cancer microenvironment." (PMID 35798917, 2022). "In vitro and in vivo experiments with four cell lines (lung cancer, breast cancer, melanoma, and colon cancer) demonstrated that hypoxia increased the expression of ACSS2 in tumor cells, which in turn increased the cellular uptake of acetate for lipid synthesis and promoted tumor progression." (PMID 35740562, 2022). "Currently, the mechanism of action of ACSS2 in breast cancer remains unclear, and more studies are needed for a better understanding." (PMID 35798917, 2022). "However, some studies have shown that breast cancers with a low ACSS2 expression have a worse prognosis." (PMID 35740562, 2022). "ACSS2 is involved in synthesis of lipids and growth of breast cancer cells in hypoxia." (PMID 33937302, 2021). "In addition, knock‐down of ACSS2 diminished tumour burden and growth in vivo in various models including colon, liver, skin and breast cancer." (PMID 33107196, 2020). "However, nuclear localization of ACSS2 increases during oxygen and serum limitation, and nuclear ACSS2 is prominent in poorly perfused, hypoxic tumor regions of a mouse model of breast cancer." (PMID 28099844, 2017). "Importantly, silencing the nuclear-cytosolic isoform of AcCoA synthetase (ACSS2), which converts acetate to AcCoA, reduced tumor growth in a xenograft model of breast cancer." (PMID 28099844, 2017). "Interestingly, another trial showed that rapamycin may also inhibit the growth of breast cancer through ACSS2 target." (PMID 39086974, 2022). "To further confirm the association between crotonate and EZH2-mediated H3K27me3 regulation, we examined the expression levels of ACSS2, EZH2, and H3K27me3 in breast cancer and adjacent normal tissues using immunofluorescence." (PMID 41544165, 2026).
breast carcinoma (continued). "Several genes strongly related to pyruvate metabolism, glycolysis/gluconeogenesis, and tyrosine metabolism, including ACSS2, were found to be significantly downregulated in PGG-treated MDA-MB-231 breast cancer cells." (PMID 35798917, 2022). "In a study related to autophagy in breast cancer, it was found that ACSS2 promoted AGT5 expression to enhance autophagy to inhibit the proliferation and metastasis of breast cancer cells induced by cadmium." (PMID 35740562, 2022). "Factors influencing acetate activity, like ACSS2, could be explored as potential drug targets for treating IHD and breast cancer." (PMID 39519507, 2024). "It Moreover, overexpression of ACSS2 was found to increase the H3K27 acetylation (H3K27ac) in the promoter region of ATG5 and to maintain autophagic flux while reducing the proliferation, migration and invasion of breast cancer cells." (PMID 35798917, 2022). "Moreover, targeting ACSS2 using CRISPR-Cas9 guides or a small-molecule inhibitor not only hinders tumor cell metabolism but also induces an anticancer immune response, thereby enhancing the effectiveness of chemotherapy in preclinical breast cancer models." (PMID 39351241, 2024).
hepatocellular carcinoma (18 papers, 2016 to 2025). A malignant tumor that arises from hepatocytes. "Furthermore, elevated ACSS2 expression levels have been implicated in adverse prognostic outcomes across various malignancies including hepatic carcinoma, renal carcinoma, and multiple myeloma." (PMID 38887280, 2024). "ACSS2 deletion in murine models of hepatocellular carcinoma resulted in diminished tumor burden, characterized by attenuated tumor proliferation and reduced invasive characteristics." (PMID 38887280, 2024). "Immunohistochemical staining revealed that ACSS2 expression was significantly greater in normal tissues than in hepatocellular carcinoma and metastatic liver cancer, indicating that the ACSS2 expression is lower in malignant tumors than in normal tissues." (PMID 38528124, 2024). "To determine the expression of ACSS2 during the course of human liver tumorigenesis, we initially compared the ACSS2 levels in tissues from normal, cirrhotic, hepatocellular carcinoma, and metastatic liver cancer." (PMID 38528124, 2024). "The high expression of ACSS1 and ACSS2 in hepatocellular carcinoma is critical for acetate-mediated histone acetylation and de novo lipogenesis." (PMID 34050894, 2022). "Some tumours, such as glioblastomas or hepatocellular carcinomas, upregulate the expression of ACSS2 to capture acetate." (PMID 35887244, 2022). "The loss of ACSS2 reduces the tumor burden of hepatocellular carcinomas in mice; in mice with ACSS2-positive hepatocellular carcinoma, liver tumors grew faster and were more aggressive." (PMID 35740562, 2022). "Since hypoxia and energy deficiency are more common in the tumor microenvironment, simulating the tumor microenvironment by culturing hepatocellular carcinoma cells found that the expression of ACSS2 increased about five-fold compared to normoxia." (PMID 35740562, 2022). "Some tumors, such as glioblastomas and hepatocellular carcinomas upregulate the expression of ACSS2 to capture acetate." (PMID 33917812, 2021). "In studies of hepatocellular carcinoma, ACSS2 knockdown was found to deacetylate HIF-2α, which, in turn, increased cell migration and invasion and induced epithelial-mesenchymal transition." (PMID 33304273, 2020). "Paradoxically, in other studies decreased expression of ACSS2 promotes metastasis and predicts poor prognosis in hepatocellular carcinoma." (PMID 33304273, 2020). "High ACSS2 expression predicted a poor prognosis in patients with renal cell carcinoma and bladder cancer, whereas low ACSS2 expression predicted a poor prognosis in gastric cancer and hepatocellular carcinoma." (PMID 31750240, 2019). "ACSS2 captures acetate as a carbon source for the proliferation of hepatocellular carcinoma." (PMID 35456988, 2022). "During hypoxia, hepatocellular carcinoma cells increase ACSS2 expression by nearly fivefold, enhancing the rate of acetate utilization and using the resultant acetyl-CoA to increase fatty acid synthesis and acetylation of histone H3 at K9, K27 and K56, which affects transcription." (PMID 35887244, 2022). "Recently, two alternative transcription start sites in the ACSS2 gene were found in hepatocellular carcinoma cells, which might lead to clarification of the dual roles of ACSS2 in facilitating and suppressing cancer invasiveness." (PMID 35798917, 2022). "Under normoxic culture conditions, hepatocellular carcinoma cells synthesize acetyl-CoA, which is transported to mitochondria as an essential energy source; in contrast, under hypoxic culture conditions, the expression of ACSS2 increases nearly fivefold." (PMID 35798917, 2022). "Recently, two alternative transcription start sites for the ACSS2 gene have been identified in hepatocellular carcinoma cells that may help explain the dual role of ACSS2 in promoting and inhibiting cancer aggressiveness." (PMID 33304273, 2020). "Furthermore, hepatocellular carcinoma upregulates the expression of ACSS2 to utilize acetate." (PMID 35798917, 2022).
hepatocellular carcinoma (continued). "Furthermore, ACSS2 was also found to be important in glioblastoma and hepatocellular carcinomas 9,10, suggesting that increased ACSS2 activity in tumors could be a fundamental mechanism that supports growth under unfavorable conditions." (PMID 28060271, 2016). "ACSS2 is upregulated in GBM and in hepatocellular carcinoma (HCC), myeloma, prostate, and bladder cancers." (PMID 36009491, 2022). "Conversely, a negative relationship exists between ACSS2 levels and hepatocellular carcinoma, with the reduction of ACSS2 in liver cancer cells enhancing their invasiveness and mobility." (PMID 38887280, 2024). "Tumor cells undergoing Warburg effect need to produce adequate amounts of acetyl-CoA, that is mainly shunted to lipid synthesis and histone modification: indeed, the absence of acetyl-CoA synthetase (ACSS2) enzyme leads to tumor burden reduction in in vivo models of hepatocellular carcinoma." (PMID 32932943, 2020). "Notably, in hepatocellular carcinoma, ACSS2 has a negative relationship with HCC malignancy, decreased expression of ACSS2 not only promotes invasion and migration ability of HCC cells, but also promotes EMT." (PMID 38887280, 2024).